FGF21 (fibroblast growth factor 21)
Diseases named in the same sentence as FGF21 in open-access papers (continued):
Sharing a sentence is not in itself a finding about the gene and the disease.
Obesity (continued). "In summary, at thermoneutrality FGF21/sTGFBR2 more effectively improves metabolic parameters in HFD-fed obese mice than in HFD-fed mice with lipodystrophy, and FGF21/sTGFBR2 decreases quantity of rBMAT only in mice with diet-induced obesity." (PMID 40663389, 2025). "This evidence paves the way for future clinical translation of FGF21 gene therapy to treat obesity, type 2 diabetes, and other metabolic diseases." (PMID 41150735, 2025). "In the basic theme quadrant, the red circle covers metabolic foundations such as obesity, adipose tissue, diabetes, liver, type 2 diabetes, high-fat diet, liver fibrosis, insulin sensitivity, metabolism, and FGF21." (PMID 40868109, 2025). "Fibroblast growth factor 21 (FGF21) is a liver-derived endogenous hormone whose pharmacologic analogs exhibit therapeutic promise in obesity, type 2 diabetes, and MASLD by regulating lipid metabolism and enhancing insulin sensitivity." (PMID 41293239, 2025). "This study aimed to analyse the relationship between changes in plasma GDF15 and FGF21 levels and the resolution of T2D or obesity improvements after bariatric surgery." (PMID 40377893, 2025). "FGF-21 is related to typ 2 diabetes, metabolic syndrome, coronary heart disease, obesity, and chronic kidney disease." (PMID 41272580, 2025). "Patients with severe obesity had significantly higher levels of circulating FGF21 than the control group." (PMID 40943431, 2025). "Overall, the combination of berberine and evodiamine mitigates obesity by enhancing browning and activating the FGF21/PGC-1α signaling pathway." (PMID 40362407, 2025). "Pharmacological studies have shown that administration of exogenous FGF21 at supraphysiological concentrations markedly improves conditions such as obesity, insulin resistance, and nonalcoholic fatty liver disease." (PMID 41234361, 2025). "Elevated FGF21 concentrations are also observed in individuals with metabolic disorders, such as type 2 diabetes and obesity, who often exhibit FGF21 resistance—a reduced biological response to FGF21 despite its increased levels." (PMID 40390366, 2025). "Fibroblast growth factor 21 (FGF21) is an endogenous liver-secreted hormone that has therapeutic potential for treating obesity, type 2 diabetes, and MASLD." (PMID 40494889, 2025). "To elucidate the underlying mechanism, we found that BBE plays a key role in ameliorating obesity by activating the FGF21/PGC-1α pathway and promoting browning." (PMID 40362407, 2025). "Furthermore, fibroblast growth factor 21 (FGF21), a metabolic hormone that is expressed in the liver and regulates glucose metabolism and lipid homeostasis is closely associated with metabolism-related diseases, such as obesity, diabetes mellitus, and nonalcoholic fatty liver disease (NAFLD)." (PMID 39910442, 2025). "Although accumulating evidence highlights FGF21’s immense therapeutic potential for metabolic disorders such as obesity, insulin resistance, and type 2 diabetes, key gaps persist in our understanding of its systemic actions." (PMID 40881124, 2025). "The paradoxical finding of high serum FGF21 levels in men with obesity is consistent with a state of FGF21 resistance, as shown in mice, similar to what occurs with leptin." (PMID 39885510, 2025). "GDF15 and FGF21 have received significant attention over the past decade for their potential as pharmacological agents to treat obesity and type 2 diabetes." (PMID 40787810, 2025). "Basic clusters include metabolic foundations (obesity, adipose tissue, FGF21) and adipokine-centered subjects (adiponectin, leptin, NASH)." (PMID 40868109, 2025). "We also demonstrated that Gnetin C ameliorates obesity and diabetes partly by increasing FGF21 expression and secretion in the liver." (PMID 41290813, 2025). "First, we found that in HFD-induced obesity, warmer environmental housing temperatures improved effectiveness of FGF21/sTGFBR2 in decreasing body weight, improving insulin resistance, reducing plasma TAG, and decreasing hepatic steatosis." (PMID 40663389, 2025).
Obesity (continued). "For example, when rodents were given intracerebroventricular injections of FGF21, their hepatic insulin sensitivity and metabolic rate increased in cases of diet-induced obesity." (PMID 39744501, 2025). "In obese animals, the treatment with the medication FGF21 enhanced energy expenditure and ameliorated diabetes and obesity." (PMID 40881124, 2025). "Obesity, in fact, is characterized by markedly elevated circulating FGF21 levels in obese mice, in rhesus monkeys fed a high-fat diet, and in overweight or obese humans." (PMID 41516073, 2025). "The large cohort and comprehensive organokine profiling studied provide valuable insights into the role of the FGF21–adiponectin axis on systemic metabolic alterations in severe obesity and their potential clinical implications." (PMID 40943431, 2025). "In preclinical studies, FGF21 lowered plasma insulin, triglycerides, liver fat,and body weight, which led to high expectations for a novel, efficacious treatment for obesity, type 2 diabetes, dyslipidemia, and MASH." (PMID 41150667, 2025). "The optimized platform effectively delivers mGLP-1/FGF21, demonstrating potent anti-obesity effects in mice through synergistic GLP-1 and FGF21 signaling." (PMID 41431190, 2025). "FGF21 and irisin exemplify this phenomenon in obesity, where their serum levels are often increased while their metabolic actions—such as enhancing glucose homeostasis and promoting lipid oxidation—are attenuated." (PMID 41515940, 2025). "In one study, obese mice treated with an mRNA for FGF21 showed reversal of obesity-related metabolic derangements, indicating that mRNA delivery of endocrine factors is feasible and can have potent effects." (PMID 41438702, 2025). "In contrast to FGF19, plasma FGF21 concentrations were elevated in patients with severe obesity, especially in those with diabetes, and were strongly associated with liver damage." (PMID 40943431, 2025). "In mice fed a high-fat diet (HFD), combined gene therapy with FGF21 and sTGFBR2 effectively mitigated 4 age-related diseases: obesity, type 2 diabetes, heart failure, and renal failure." (PMID 40663389, 2025). "Future preclinical studies using both FGF21 and GDF15 analogues in combination should shed light on their therapeutic potential to attenuate obesity and associated comorbidities." (PMID 40897647, 2025). "Previous studies have tested multiple therapeutic combinations with FGF21 or FGF21 alone and have found that FGF21 alone is sufficient to improve insulin sensitivity and reduce obesity in HFD-fed mice." (PMID 40663389, 2025). "This study demonstrated that impaired autophagy in PTECs during aging or obesity induces fibroblast growth factor 21 (FGF21) production, known for its anti-aging and anti-obesity properties." (PMID 40131605, 2025). "Fibroblast growth factor 21 (FGF21) is a key hormone for metabolic homeostasis under conditions such as obesity, aging and diabetes." (PMID 41516073, 2025). "FGF21 and its analogues are currently being investigated in clinical trials for the treatment of obesity, type 2 diabetes, and fatty liver disease, while the clinical potential of rGDF15 for obesity treatment is also being explored." (PMID 40787810, 2025). "An emerging phenomenon – FGF21 resistance in obesity, due to diminished sensitivity of its coreceptor β‐klotho, raises concern on the rewiring energy balance in dual MASLD‐obesity burden." (PMID 39495024, 2025). "Numerous clinical trials have been registered to evaluate the efficacy of FGF21 analogues in the treatment of obesity, T2DM, hypertriglyceridemia, and MASH." (PMID 40006605, 2025). "This study demonstrates that the combination of berberine and evodiamine effectively combats obesity by activating the FGF21/PGC-1α signaling pathway and promoting browning." (PMID 40362407, 2025). "GDF15 and FGF21 are stress‐responsive cytokines whose levels are increased in several diseases, including obesity and T2D, being most of them age‐related disorders." (PMID 40377893, 2025).
Obesity (continued). "Recent advancements in FGF21-based gene therapy for obesity and insulin resistance have demonstrated encouraging results, showing the long-term potential of this approach." (PMID 41150735, 2025). "In this sense, the important relationship of growth differentiation factor 15 (GDF15) and fibroblast growth factor 21 (FGF21) with metabolic regulation has exponentially increased the study of both proteins in relation to obesity and its comorbidities." (PMID 40377893, 2025). "Paradoxically, FGF-21 is elevated in various pathological conditions such as obesity, type 2 diabetes, and non-alcoholic fatty liver disease, a phenomenon often interpreted as FGF-21 resistance or a compensatory response to chronic metabolic stress." (PMID 40868993, 2025). "FGF21 expression is elevated in both obese humans and mice, and the exogenous administration of FGF21 has been shown to mitigate obesity by reducing inflammation, promoting the browning of white adipose tissue, and enhancing heat production." (PMID 40362407, 2025). "Serum concentrations of FGF-19 and FGF-21 were measured in 137 individuals with obesity and different degrees of insulin resistance matched by sex, age, and body adiposity and compared to 33 lean individuals." (PMID 41155711, 2025). "To date, six randomized clinical trials have evaluated the therapeutic potential of four human FGF21 analogs or mimetics in T2DM or obesity." (PMID 41234361, 2025). "The recognition that increased serum FGF21 expression in patients with obesity/type 2 diabetes (T2D) compensates for pathologic metabolic changes led us to further dissect the role of FGF21 in the ischemic cascade after stroke." (PMID 40021824, 2025). "FGF-21 has recently drawn increasing interest as a therapeutic target for obesity-related metabolic disorders, including MAFLD, mainly because of its effect on lipid and carbohydrate metabolism." (PMID 40430125, 2025). "Under disease states, obesity/diabetes attenuates catecholamine and FGF21 responsiveness; however, endurance training can still improve myocardial mitochondrial function via the IGF-1 pathway." (PMID 41000109, 2025). "Key organokines such as fibroblast growth factors FGF19 and FGF21, adiponectin, galectin-3, irisin, and leptin represent well-characterized mediators of inter-organ communication with direct implications in obesity-related metabolic dysfunction." (PMID 40943431, 2025). "FGF21 analogues are under investigation for metabolic diseases, such as obesity, dyslipidemia, T2DM, and MASLD/MASH." (PMID 40243151, 2025). "In vitro experiments have found that apoptosis caused by iron-dependent lipid peroxidation induced by the transcription factor BACH1 can stimulate the secretion of FGF21 and inhibit obesity in mice on a high-fat diet." (PMID 40656191, 2025). "Since their plasma levels increase with obesity, it has been proposed that GDF15 and FGF21 jointly impose a cap on weight gain during diet‐induced obesity." (PMID 40787810, 2025). "In summary, our current transcriptomic data suggest a role of hepatic FGF21 signaling in the beneficial effects of DHA on MASLD progression in obesity and aging." (PMID 41373837, 2025). "FGF21 is an endocrine hormone that improves glucose and lipid metabolism and has been proposed as a potential therapeutic target for obesity-related metabolic disorders." (PMID 41470800, 2025). "A longitudinal study in a subset of men with obesity following bariatric surgery revealed a unique FGF21 trajectory with a sharp peak at one month post-RYGB that correlated with metabolic and reproductive improvements." (PMID 39885510, 2025). "FGF21 analogs have been shown to ameliorate dyslipidemia and enhance adiponectin levels in individuals with obesity and T2D, though their effects on glycemic control remain limited." (PMID 40629349, 2025).
Obesity (continued). "We are unsure of survodutide's impact on earlier or later stages of MASLD given our unclear physiological understanding of NNMR on MASLD progression, and a long‐term study is needed to determine if FGF21 resistance affects the obesity group." (PMID 39495024, 2025). "The circulating concentrations of GDF15 and FGF21 were significantly increased with obesity and further increased with IGT and T2D." (PMID 40828431, 2025). "A notable feature of the subset with high circulating FGF21 levels was a higher mean BMI which verged on obesity." (PMID 40788112, 2025). "Along the course of our study, a recent report indicated that adipocyte DNMT3a mediates obesity-induced insulin resistance via increasing DNA methylation at the Fgf21 gene." (PMID 40666843, 2025). "documented the therapeutic advantages of FGF21 in addressing obesity‐induced hyperglycemia, hypertriglyceridemia, and peripheral IR by activating its downstream mediator, adiponectin." (PMID 39764565, 2025). "Deficiencies in autophagy lead to mitochondrial dysfunction, which subsequently elevates FGF21 levels, thereby aiding in the prevention of diet-induced obesity and insulin resistance while promoting muscle mass and function." (PMID 40136413, 2025). "FGF-21 is produced by metabolic active tissues such as the liver but also the adipose tissue, somehow explaining the supraphysiological hormone concentration and the impaired hormonal response in obesity defined as FGF-21 resistance state." (PMID 40059147, 2025). "Both obesity and fatty liver accumulation are independent factors of chronic high FGF21 levels, which is considered an FGF21-resistant state and related to the onset of type 2 diabetes and cardiovascular diseases." (PMID 38178259, 2024). "Clinical studies reported that administration of FGF21 analogues to obese participants improved obesity, glucolipid parameters, and hepatic steatosis." (PMID 39354624, 2024). "This increased respiration and protection from diet induced obesity was dependent on BAT-derived FGF21 secretion." (PMID 38212382, 2024). "Similar to rodents, both male and females that suffer from obesity exhibit higher levels of serum FGF21 compared to lean counterparts, suggesting FGF21 resistance with increased levels of adiposity." (PMID 39087083, 2024). "In another study, when adjusted for age, sex, and BMI, FGF21 levels were twofold higher in individuals with metabolically unhealthy than people with metabolically healthy obesity." (PMID 39008201, 2024). "Specifically, we sought to compare the levels of NRG4, FGF21, and irisin between metabolically healthy and unhealthy individuals with obesity." (PMID 39008201, 2024). "FGF21's therapeutic properties include reducing obesity, dyslipidaemia, and hyperglycemia, which can help treat metabolic disorders, autophagy, and apoptosis." (PMID 38333506, 2024). "In mice, FGF21 induces adipocyte production of adiponectin, which in turn acts as an indispensable downstream effector, conferring protective effects of FGF21 against obesity-induced metabolic complications and atherosclerosis." (PMID 38321233, 2024). "Our study shows that FGF21 increase is particularly expressed in obesity and obesity-related conditions, and it is an independent predictor of all-cause mortality." (PMID 39302236, 2024). "The hepatokine FGF21, whose expression increases with sweet food consumption and obesity, and which can have endocrine and autocrine effects, acts as an adaptation factor." (PMID 39596499, 2024). "Studies have found that enoxacin inhibits the expression of miR-34a-5p in adipocytes, thereby enhancing FGF21 signaling to promote oxidative metabolism and combat obesity." (PMID 39767659, 2024). "FGF21 is postulated to play an adaptive role in response to physiologic and metabolic stressors and is found elevated in poor metabolic health, including obesity, type 2 diabetes mellitus, and insulin resistance." (PMID 38750219, 2024).
Obesity (continued). "In line with the current experimental results, various studies posit that a decrease in FGF21 results in obesity." (PMID 38736904, 2024). "Given the superior role of FGF21 in improving metabolic disorders, developing FGF21 analogs is also a strategy to combat obesity." (PMID 38644407, 2024). "Currently, several studies consider FGF21 a promising target for treating obesity and metabolic diseases." (PMID 38673797, 2024). "Current FGF21-related drugs and therapies primarily target obesity and dysregulated glucose and lipid metabolism, including conditions such as liver steatosis, T2DM, and viral hepatitis." (PMID 38902808, 2024). "Animal studies have shown that FGF21 has multiple beneficial effects on obesity and its related metabolic complications." (PMID 39100807, 2024). "After 3 months, reductions in TNF-α, IL-6, and FGF-21 levels were significant in individuals with obesity/overweight and NAFLD." (PMID 38608067, 2024). "One major hurdle is the presence of resistance in individuals with obesity, such as leptin resistance and FGF21 resistance, which reduces responsiveness to the metabolically favorable actions of these adipokines." (PMID 39872218, 2024). "Of note, participants with high serum levels of FGF21 more frequently had metabolic complications, such as hypertension, obesity, diabetes, hypercholesterolemia, and hypertriglyceridemia." (PMID 39302236, 2024). "The levels of FGF21 were significantly higher in the serum of the obese group with respect to overweight subjects, showing the involvement of FGF21 in the alterations of lipid metabolism occurring in obesity-related diseases." (PMID 38541057, 2024). "Beneficial FGF21 function has encouraged many attempts to utilize it as a therapeutic agent to treat obesity-related comorbidities, such as type 2 diabetes mellitus and dyslipidemia." (PMID 39452947, 2024). "It has been reported that FGF21 levels increase with obesity, insulin resistance, type 2 diabetes, and non-alcoholic fatty liver disease." (PMID 39211324, 2024). "This work seeks to elucidate how gut microbiota-derived changes contribute to FGF21 regulation and metabolic adaptations, providing a basis for future strategies to treat metabolic diseases such as obesity and diabetes." (PMID 39683422, 2024). "The positive metabolic effects of FGF21 administration, known for promoting health, coincide with elevated hormone levels observed in obesity and diabetes." (PMID 38203812, 2024). "Studies relate FGF21 resistance in patients with obesity to the release of pro-inflammatory molecules and microRNAs, leading to an increase in FGF21 plasma levels and decreased expression of the FGF21 receptor complex." (PMID 39597026, 2024). "FGF21 serum levels are also increased in metabolic conditions such as obesity, type 2 diabetes and cardiovascular disease." (PMID 39302236, 2024). "When expressed at an optimal level, FGF21 protects animals from obesity induced by a diet rich in fat and carbohydrates." (PMID 39902162, 2024). "Extensive validation in rodent models has established the therapeutic potential of FGF21 for obesity and related metabolic disorders." (PMID 38609395, 2024). "Nevertheless, the existing clinical evidence indicates that levels of FGF21 are unexpectedly elevated in HF, suggesting the presence of a state of FGF21 resistance similar to that observed in obesity." (PMID 38333506, 2024). "Previous research has established that FGF21 is a significant marker for obesity, as it often correlates with the degree of adiposity and the success of weight loss efforts." (PMID 39194718, 2024). "Previous studies have focused on the pharmacological effects and clinical potential of FGF21 in cardiovascular diseases and metabolic diseases such as diabetes mellitus, obesity, and insulin resistance." (PMID 37864659, 2024).